TOGARAM2 (TOG array regulator of axonemal microtubules 2)
Synonyms: FAM179A; FLJ43249; LOC165186; Crescerin-2
Tractability: Antibody: the Human Protein Atlas places it where antibodies can reach. PROTAC: ubiquitination databases record sites on it.
Gene: Protein-coding gene on chromosome 2 (28,956,506 to 29,052,236, forward strand). Ensembl gene ENSG00000189350.
Subcellular location (Human Protein Atlas): Nucleoplasm; Plasma membrane
Gene Ontology:
Molecular function: microtubule binding
Biological process: microtubule cytoskeleton organization
Cellular component: cilium; cytoplasmic microtubule
Genetic constraint (gnomAD): Loss-of-function variants: 83 observed, 83.72 expected, observed/expected ratio (o/e) 0.99, 90% interval 0.83 to 1.19. The upper end of that interval is the gene's LOEUF score, 1.19, which puts it in group 5 of 6, group 1 being the genes least tolerant of losing a copy. Missense variants: 1,240 observed, 1,237 expected, observed/expected ratio (o/e) 1, 90% interval 0.96 to 1.05. Synonymous variants: 575 observed, 498.98 expected, observed/expected ratio (o/e) 1.15, 90% interval 1.08 to 1.24.
Homologues: Orthologues: chimpanzee TOGARAM2 (97% identical), macaque TOGARAM2 (88% identical), dog TOGARAM2 (75% identical), pig TOGARAM2 (73% identical), rat Togaram2 (73% identical), mouse Togaram2 (71% identical), tropical clawed frog togaram2 (39% identical), Caenorhabditis elegans che-12 (18% identical), Drosophila melanogaster chb (12% identical), Caenorhabditis elegans cls-1 (9% identical), Caenorhabditis elegans cls-3 (7% identical), Caenorhabditis elegans cls-2 (6% identical). Paralogues in human: TOGARAM1 (32% identical), CLASP1 (16% identical), CLASP2 (16% identical).
Diseases named in the same sentence as TOGARAM2 in open-access papers:
TOGARAM2 is named in the same sentence as 4 diseases in open-access papers, as found by Europe PMC text mining. Sharing a sentence is not in itself a finding about the gene and the disease. The quoted sentences say what the papers report.
cervical cancer (1 paper, 2024). A primary or metastatic malignant neoplasm involving the cervix. "To begin to understand the functional association between TAZ and TOGARAM2 in cervical cancer, we first investigated TOGARAM2’s expression in a panel of cell lines." (PMID 38987584, 2024). "To determine the importance of TAZ-mediated upregulation of TOGARAM2 in HPV18+ cervical cancer, we generated polyclonal TOGARAM2 KD HeLa cell lines using two different shRNA." (PMID 38987584, 2024). "We identify the poorly understood gene TOGARAM2 as a TAZ target that plays a critical role in mediating the oncogenic functions of TAZ in HPV18+ cervical cancer cells." (PMID 38987584, 2024). "To understand whether TOGARAM2 is important for the TAZ–dependent phenotype in cervical cancer cells, we overexpressed TOGARAM2 in TAZ KD HeLa cells." (PMID 38987584, 2024). "Taken together, our data demonstrate that TOGARAM2 mediates aspects of the oncogenic functions of TAZ, particularly associated with cell migration and invasion and suggests that TOGARAM2 is a potential oncogene in HPV18+ cervical cancer cells." (PMID 38987584, 2024). "Our data support that TOGARAM2 is a TAZ-dependent gene that may function to promote cervical cancer progression." (PMID 38987584, 2024). "Finally, we investigated the clinical relevance of TOGARAM2 expression in cervical cancer patients." (PMID 38987584, 2024).
cancer (1 paper, 2024). A tumor composed of atypical neoplastic, often pleomorphic cells that invade other tissues. "As TAZ is frequently linked to aggressive and metastatic phenotypes, it is possible TOGARAM2 serves as a TAZ target in other non-HPV driven cancers, and further studies will be required to confirm this." (PMID 38987584, 2024). "This analysis identified TOGARAM2 as a previously uncharacterised TAZ target and demonstrates its role as a key effector of TAZ-mediated proliferation, migration and invasion in HPV18+ cancers." (PMID 38987584, 2024).
TOGARAM2 also shares sentences with these, for which no sentence is quoted: breast carcinoma (1 paper); prediabetes (1).